CAV1 (caveolin 1)
Diseases named in the same sentence as CAV1 in open-access papers (continued):
Sharing a sentence is not in itself a finding about the gene and the disease.
atherosclerosis (continued). "To conclude, the advancement in the understanding of CAV‐1 and its influence on lipid homoeostasis and atherosclerosis could be a new approach for the treatment of metabolic syndrome." (PMID 28149711, 2016). "Cav-1 may positively or negatively influence the development of atherosclerosis, depending on the cell type and the metabolic pathways regulated by this protein." (PMID 25756273, 2015). "Caveolin-1 (Cav-1), occupying the calcium/calmodulin binding site of endothelial NO synthase (eNOS) and then inhibiting nitric oxide (NO) production, is also involved in the development of atherosclerosis." (PMID 24926683, 2014). "Our previous study revealed that CAV-1 may be important in the prevention and treatment of atherosclerosis." (PMID 24475013, 2014). "Although this is not explored in the current study, it is logical to hypothesize that AngII-induced atherosclerosis in ApoE−/− mouse is, at least, partly mediated by the increased Cav-1-mediated suppression of eNOS activity." (PMID 23469284, 2013). "In addition, endothelial Cav-1 was shown to play an important role in other pathologies such as atherosclerosis, tissue ischemia, lung injury, or pathological angiogenesis and inflammation." (PMID 26605130, 2012). "However, the mechanistic aspects of the involvement of Cav-1 in human atherosclerosis remain to be elucidated." (PMID 26605130, 2012). "Given theimportance of EC apoptosis in the onset and development of atherosclerosis, future studies should be performedto provide more insight in this functional implication of the substantiallylowered Akt activation in cells with less caveolin-1." (PMID 20111626, 2009). "Because of theimportance of caveolin-1 in endothelial signaling, it is a potential target forclinical applications, for example, in tumor angiogenesis and atherosclerosis.Therefore, the role of caveolin-1 in the EC shear stress response is definitelyworth studying in more detail." (PMID 20111626, 2009). "The present study identifies Cav-1 as a potential stabilizing factor in human atherosclerosis." (PMID 18596970, 2008). "Previous reports have shown other in vivo actions of Cavtratin targeting inflammation, tumor progression and right ventricle hypertrophy, We provide evidence showing that Cav-1 might act as a novel stabilizing factor in human atherosclerosis." (PMID 18596970, 2008). "Caveolin-1 (Cav-1) is a regulatory protein of the arterial wall, but its role in human atherosclerosis remains unknown." (PMID 18596970, 2008). "This study demonstrates that Cav-1 is a relevant regulator of aortic endothelial autophagy and suggests that pharmacological inhibition of Cav-1-activated autophagy may provide a potential therapeutic strategy for cardiovascular diseases including atherosclerosis." (PMID 38505420, 2024). "Therefore, the protection against atherosclerosis in Cav-1 depleted models may be also related to a reduced oxidative and inflammatory environment." (PMID 37240214, 2023). "Cav-1 is traditionally considered a cholesterol-binding protein that is able to shuttle cholesterol between various cell membranes, and acts as a central regulator of cholesterol metabolism during atherosclerosis, which varies depending on the cell type involved." (PMID 36407436, 2022). "In addition, overexpression of Cav1 accelerated atherosclerosis in Apoe−/− mice." (PMID 33723357, 2021). "However, the role of Cav-1 during atherosclerosis is context and cell-type dependent." (PMID 34122329, 2021). "Previous studies have illustrated that CAV-1 may be involved at the earlies stages of atherosclerosis development through increased LDL particle transcytosis, endothelial cells activation, and induced protherogenic molecule CD36 and vascular cell adhesion molecule-1 expression." (PMID 27124120, 2016). "It is known that lipid transport proteins (CAV-1, ABCA1, SREBP-1, LXR, etc.)and inflammation (HMGB1, CXCL13, TIMP-1, etc.)in blood vessels mediate the formation of atherosclerosis." (PMID 38622667, 2024).
atherosclerosis (continued). "For instance, Cav-1 absence in aortic endothelial inhibits atherosclerosis by attenuating LDL transcytosis and enhancing autophagic flux, while in macrophages Cav-1 promotes THP-1 differentiation, ABCA1 expression and cholesterol efflux." (PMID 36407436, 2022). "Taken together, our findings demonstrated that salidroside protected against atherosclerosis by inhibiting LDL transcytosis through enhancing the autophagic degradation of active Src and caveolin-1." (PMID 32685103, 2020). "On balance, these studies show that inhibition of caveolin-1 or reduction in cholesterol might reduce endothelial permeability to LDL and, thereby, atherosclerosis." (PMID 40013359, 2025). "It has been shown that the absence of Cav-1 attenuates the initiation of atherosclerosis by promoting autophagic flux." (PMID 37240214, 2023). "A new study showed SIRT6 could act on and deacetylate caveolin-1 in ECs, which activated autophagic degradation of caveolin-1 and inhibited high glucose stimulated LDL transport, which further inhibited the formation of atherosclerosis in diabetes." (PMID 35677446, 2022). "Taken together these data show the role of Cav-1 in the regulation of RCT in HAECs by HIV which can lead to endothelial cell dysfunction and provides a novel candidate to target for modulating HIV infection related atherosclerosis and cardiovascular diseases." (PMID 26169283, 2015). "However, some contrary evidence suggests that the absence of Cav-1 and increased autophagy play a protective role in atherosclerosis." (PMID 41030451, 2025). "Therefore, targeting the Cav-1/miR-7-5p/SQSTM1 axis may restore endothelial homeostasis and mitigate atherosclerosis." (PMID 41030451, 2025). "Combined with analysis of cav-1 and total eNOS expression on mouse LCAs and aortas exposed to different flow conditions, these results point to a known mechanosensory, GCX, as a responsible agent for differential expression of cav-1 and eNOS in relation to atherosclerosis development." (PMID 30563532, 2018). "Interestingly, reconstitution of only endothelial Cav1 increased the aortic plaque burden and ICAM-1 and VCAM-1 expression back to control levels, suggesting that caveolin proteins mediate endothelial inflammation leading to atherosclerosis." (PMID 27027326, 2016). "Therefore, increased hepatic CAV‐1 in the DKO mice could also be beneficial for the efficient removal of circulating oxLDL, preventing atherosclerosis development." (PMID 28149711, 2016). "The absence of Cav-1 leads to the release of ATG5 from the Caveolae, the increase of autophagosome formation, and the increase of autophagy flux, thus reducing inflammation and atherosclerosis." (PMID 41030451, 2025). "Since depletion of Caveolin-1 leads to a reduction of SMAD1/5, Caveolin-1, rather than ALK1 or BMP9, could be an interesting target for the treatment of vascular diseases, especially in early atherosclerosis." (PMID 36171573, 2022).
ovarian carcinoma (72 papers, 2002 to 2025). A malignant neoplasm originating from the surface ovarian epithelium. "Overexpression of CAV1 and anti-miR-1246 treatment significantly sensitized ovarian cancer cells to paclitaxel and reduced tumor mutation burden in preclinical models." (PMID 35158857, 2022). "The previous studies have demonstrated that the decreased expression of stromal CAV1 promotes tumor aggressiveness in ovarian carcinoma and low CAV1 mRNA expression in ovarian cancer tissues was associated with a worse prognosis." (PMID 32401768, 2020). "Meanwhile, loss of Cav-1 was frequently observed in various types of malignancies such as breast and colon cancers and ovarian carcinomas." (PMID 26431273, 2015). "Low CAV1 expression has been linked to cisplatin resistance in oral squamous cell carcinoma while it is a putative tumour suppressor candidate in ovarian cancer." (PMID 26205780, 2015). "In a study of caveolin-1 in ovarian cancer, immunohistochemical analysis of caveolin-1 shows normal expression of caveolin-1 in the surface epithelium and in the underlying stroma of normal ovary." (PMID 25594072, 2014). "Moreover, the interaction between miR-1246 and caveolin-1 (CAV1) via TDEs caused PTX resistance in ovarian cancer by upregulating the expression of ABCB1, which is the gene encoding P-gp." (PMID 36359776, 2022). "Moreover, simultaneous expression of caveolin-1 and E-cadherin in ovarian cancer cells stabilized adherens junctions through inhibition of src-related kinases whereas loss of E-cadherin enhanced ovarian cancer metastasis through up-regulation of α5-integrin." (PMID 23144806, 2012). "In ovarian cancer, specifically, folate receptor alpha has a role in the downregulation of the tumor suppressor caveolin-1 (cav-1), which is important for cell proliferation." (PMID 40507303, 2025). "Cav-1 overexpression has also been associated with increased MMP production and invasiveness in hepatocellular and ovarian carcinoma models." (PMID 39244591, 2024). "recently demonstrated that exosomal miR-1246 released in abundance from ovarian cancer cells confers chemo-resistance via targeting the Cav1/p-gp/M2-type macrophage axis." (PMID 37424776, 2023). "An exosomal miRNA, miR-1246 was found to directly target and downregulate CAV1 in ovarian cancer cells, leading to an increase in the expression of PDGFRβ and P-gp." (PMID 35158857, 2022). "Ovarian cancer cells can induce the upregulation of MCT4 and loss of expression of Cav-1 via autophagy, leading to a microenvironment favorable to tumor growth." (PMID 35681617, 2022). "EVs derived from ovarian cancer cells abundantly express exosomal miR-1246, which confers resistance to paclitaxel through inhibition of Caveolin-1 (CAV-1) and increased levels of multidrug resistance protein 1 (MDR1)." (PMID 35646668, 2022). "Zeng 14 and other studies found the correlation between the expression of CAV1 and clinicopathological parameters of ovarian cancer and its relationship with the prognosis." (PMID 34234869, 2021). "Exosomal CAV1 levels in ovarian cancer patient plasma were significantly down-regulated (P < 0.001), when compared with healthy controls." (PMID 34234869, 2021). "Next, we investigated plasma exosomal CAV1 levels in ovarian cancer patients at different disease stages." (PMID 34234869, 2021). "The low plasma levels of exosomal CAV1 in ovarian cancer patient plasma were related to FIGO stages, grades and lymph node metastasis (all P < 0.01)." (PMID 34234869, 2021). "The AUROC of plasma exosomal CAV1 was 0.76 (95% CI: 0.68-0.82) for DFS prediction in ovarian cancer patients." (PMID 34234869, 2021). "In summary, our study revealed that exosomal CAV1 levels in plasma of ovarian cancer patients were significantly downregulated." (PMID 34234869, 2021). "First, although this was a large study evaluating plasma exosomal CAV1 levels in ovarian cancer patients, more patients from multiple centers need to be validated." (PMID 34234869, 2021).
ovarian carcinoma (continued). "The objective of this study was to evaluate the clinical significance of Cav-1 expression in invasive epithelial ovarian cancer (OvCa)." (PMID 34813586, 2021). "In recent years, there has been an increase in studies on the expression and biological roles of CAV1 in ovarian cancer." (PMID 34234869, 2021). "The levels of exosomal CAV1 in patient plasma were significantly higher in ovarian cancer patients with FIGO stages I/II, low grade (1/2) than in those with FIGO stages III/IV disease and high grade (3/4)." (PMID 34234869, 2021). "To date, this is the first study to evaluate the levels of plasma exosomal CAV1 and determine its prognostic value in patients with ovarian cancer." (PMID 34234869, 2021). "We examined plasma exosomal CAV1 levels in ovarian cancer patients and healthy controls using ELISA." (PMID 34234869, 2021). "The levels of exosomal CAV1 in patient plasma were significantly higher in ovarian cancer patients with FIGO stages I/II, low grade (1/2) than FIGO stages III/IV disease and high grade (3/4) (both P < 0.01)." (PMID 34234869, 2021). "Recent reports have also suggested an oncogenic role of CAV-1 in pancreatic, breast and ovarian cancers." (PMID 34762666, 2021). "The AUROC of plasma exosomal CAV1 was 0.76 (95% CI: 0.68-0.82) for DFS prediction in ovarian cancer patients, with a sensitivity 52.9 (95% CI: 42.8-62.9) and a specificity 88.7 (95% CI: 77.0-95.7)." (PMID 34234869, 2021). "Of special attention is the description of the expression levels of genes such as POSTN, CHI3L1, CAV-1, IRS1, DCN, which according to literature data are associated with diseases such as POI, PCOS, and ovarian cancer." (PMID 34827207, 2021). "Compared with healthy controls, exosomal CAV1 levels in ovarian cancer patient plasma were significantly downregulated." (PMID 34234869, 2021). "We also investigated plasma exosomal CAV1 levels in ovarian cancer patients at different disease stages." (PMID 34234869, 2021). "Investigations in OvCa have found Cav-1 functions as a tumor suppressor gene and is significantly downregulated in ovarian cancer cell lines and carcinomas which promotes tumor growth, survival, invasion, and metastasis." (PMID 34813586, 2021). "Four different CAF subsets identified by analyzing specific CAF markers (FAP, integrin β1/CD29, αSMA, S100‐A4/FSP1, PDGFRβ, and CAV1) have been reported and related to immune modulation in human breast and ovarian cancers." (PMID 32909687, 2020). "In some cancers, such as colorectal cancer and ovarian cancer, Cav-1 expression is down-regulated, suggesting that Cav-1 can inhibit such cancer development." (PMID 31991790, 2020). "Ectopic expression of Cav-1 leads to growth inhibition, activation of caspase-3, reduction of colony formation, and cell invasiveness in ovarian cancer." (PMID 31759347, 2019). "In ovarian cancer, it was found that the expression of Cav-1 was frequently presented in advanced ovarian carcinomas and more expressed at cell membrane with metastasis and poor-survival tumors." (PMID 31759347, 2019). "Overexpression of Cav-1 can promote apoptosis of ovarian cancer cells after galectin-3 and paclitaxel treatment." (PMID 31759347, 2019). "Cav-1 is critical in the uptake and high cytotoxicity of Cisplatin Nanocapsules through caveolae-mediated endocytosis in ovarian carcinoma cells." (PMID 31759347, 2019). "Consistently, Cav-1 is reduced in ovarian cancer cell lines compared to human ovarian surface epithelial (HOSE) cell lines and up-regulated following progesterone (P4) treatment." (PMID 31759347, 2019). "Stromal Cav-1 expression in breast and ovarian cancer is driven in concert with tumour cell oncogene expression with the resulting oxidative stress causing a switch from normal to CAF-like phenotype." (PMID 29416729, 2018). "This decrease in Cav-1 expression (mRNA and protein level) was also seen in gastric, colon, and ovarian cancer cell lines." (PMID 25756273, 2015).
ovarian carcinoma (continued). "In an ovarian carcinoma setting, ectopic expression of Cav1 stabilized adherens junctions through inhibition of Src-related kinases." (PMID 25550395, 2015). "CAV1 expression is down-regulated in ovarian cancer cell lines but expression can be restored by treating the cells with 5-AZA." (PMID 26112043, 2015). "Downregulation of Cav-1 and its tumor suppression function has been validated in breast, colon, and ovarian cancer and soft-tissue sarcomas." (PMID 26431273, 2015). "NANOG1 overexpression in ovarian cancer cells has been shown to enhance migration capacity, which is accompanied by decreased E-cadherin, caveolin-1, FOXJ1, and FOXO1 expression." (PMID 26087476, 2015). "We therefore, initially examined the expression of BRCA1 and caveolin-1 in a BRCA1-mutant human ovarian cancer cell line, UWB1.289." (PMID 25594072, 2014). "In ovarian carcinoma cell lines this down-regulation required DNA methylation, and transfection of ovarian cancer cells with caveolin-1 decreased cell survival." (PMID 18949068, 2007). "This indicates that Cav-1-autophagy is involved in the pathogenesis of hereditary ovarian cancer." (PMID 41030451, 2025). "Low levels of CAV1 indicate a poor prognosis in ovarian cancer." (PMID 40008006, 2025). "Furthermore, ovarian cancer cells can also transfer their exosomal miR-1246 selectively to M2-type macrophages, which then produce lower CAV-1 mRNA levels." (PMID 35646668, 2022). "Additionally, miRNA-containing EVs conferred chemo-resistance in ovarian cancer via regulating the Cav1/p-gp/M2-type macrophage axis." (PMID 33407591, 2021). "Therefore, our goal in this study is to evaluate the levels of plasma exosomal CAV1 and determine its prognostic value in patients with ovarian cancer." (PMID 34234869, 2021). "Finally, we assessed the prognostic value of plasma exosomal CAV1 levels in ovarian cancer patients." (PMID 34234869, 2021). "Studies are needed to glean mechanistic insights into how reduced levels of Cav-1 in the stroma may promote transformation to ovarian carcinoma." (PMID 34813586, 2021). "Another study found that CAV1 that suppresses the progression of ovarian cancer is directly inhibited by miR-96-5p, indicating that CAV1 may be regulated by miRNAs in carcinogenesis." (PMID 33886809, 2021). "Association between CAV1 and ATG4C protein expression in epithelial ovarian cancer tissues." (PMID 32401768, 2020). "Furthermore, previous studies have indicated that CAV1 functions as a tumor suppressor in ovarian carcinoma cells, and stromal CAV1 is lost in the majority of malignant and borderline ovarian carcinomas." (PMID 32401768, 2020). "CAV1 is often expressed in advanced-stage ovarian carcinoma with metastasis." (PMID 32401768, 2020). "Moreover, CAV1 is present in several subcellular locations including the nucleus of ovarian cancer cells." (PMID 32825247, 2020). "Furthermore, expression of CAV-1 in the ovarian carcinoma cell line OVCAR-3, resulted in suppression of tumor cell survival in vitro, suggesting that the CAV-1 gene is likely to act as a tumor-suppressor gene in human ovarian epithelium." (PMID 31889941, 2019). "CD44 was knocked down by small interfering RNA, the expression of Snail, ZEB1, and Caveolin-1 in a stable Snail-expressing ovarian cancer cell line HO8910PM-Snail (HOPM-Snail) and its control cell line HO8910PM-vector (HOPM) was detected by western blotting analysis." (PMID 31497537, 2019). "Besides, it was revealed that Cav-1 promoted chemotherapy resistance in ovarian cancer through inhibiting cell apoptosis in the Notch-1/Akt/NF-κB pathway." (PMID 31759347, 2019). "Presumably, up-regulation of Caveolin-1 in CD44 knockdown ovarian cancer cells may partially contribute to the favorable prognosis of ovarian cancer patients." (PMID 31497537, 2019).